APOA1 (apolipoprotein A1)
Diseases named in the same sentence as APOA1 in open-access papers (continued):
Sharing a sentence is not in itself a finding about the gene and the disease.
Anxiety (4 papers, 2022 to 2026). Intense feelings of nervousness, tension, or panic often arise in response to interpersonal stresses. "•Deep phenotyping showed increased levels of the cytokine CCL2 and brain-derived neurotrophic factor, reduced apolipoprotein A1 and ipsilateral dorsal root ganglion atrophy, and with increased anxiety were associated with CPIP." (PMID 39909798, 2025). "There are no statistical differences in CCMR components including pre‐pregnancy BMI, SDP, DBP, RPG, ApoA1 and TG, maternal anxiety score, or depressive symptom score between two groups." (PMID 41085141, 2026). "Based on our exploratory study, we provide clinicians with additional diagnostic tools for CPIP, including DRG MRI, ApoA1, and BDNF serum levels, and anxiety screening with the STAI test." (PMID 39909798, 2025). "Deep phenotyping based on the pathophysiology of nerve damage and persistent low-grade inflammation identified ipsilateral DRG atrophy, in combination with low ApoA1, elevated BDNF, and high anxiety levels, as the best additional diagnostic tools." (PMID 39909798, 2025). "A cluster of DRG atrophy, BDNF, ApoA1, and anxiety correlated best with the diagnosis." (PMID 39909798, 2025).
aortic stenosis (4 papers, 2024 to 2025). Aortic valve stenosis is a aortic valve disease caused by the incomplete opening of the aortic valve. "In another study, an elevated apoA/apoA-1 ratio was associated with an increased incidence of aortic stenosis." (PMID 40870420, 2025). "Subjects who developed aortic stenosis during follow-up had a higher mean age at baseline (54.4 vs 44.6) and a higher proportion of males, as well as higher fasting glucose, lipid levels, apoB/apoA-1 ratio and CRP." (PMID 39915078, 2025).
babesiosis (4 papers, 2014 to 2025). Babesiosis refers to a condition caused by microscopic parasites that infect the red blood cells. "By contrast, statistically significantly higher ApoA-1 concentrations in dogs with canine babesiosis compared to healthy ones were detected in another study." (PMID 41437958, 2025). "On the other hand, a higher number of phosphorylated proteins was found in control samples in case of ApoA1 at S220 (5 controls vs. none in babesiosis samples), Chromogranin A at S190 (4 controls vs. 1 babesiosis) and Fibrinogen α at S22 (9 controls vs. 6 babesiosis)." (PMID 30485286, 2018).
breast tumor (4 papers, 2013 to 2021). "In conclusion, APOA1/C3/A4/A5 copy number loss was more prevalent in luminal breast tumors among East Asian women aged <50 years, and its immunomodulatory effect on the tumor microenvironment possibly plays various roles in the tumor biology of East Asian patients." (PMID 34226567, 2021). "To compare the GEs of the APOA1/C3/A4/A5 in breast tumors of the age <50 years/ER+/HER2− subgroup between Asians and Caucasians, we retrieved the raw data from the GSE2019420 and GSE4525521 datasets, which included tumors from multiple races." (PMID 34226567, 2021). "ApoA1 was found in breast tumors, and its amount was correlated positively with chemotherapy resistance in malignant tumors." (PMID 23829168, 2013). "Upon analysis of APOA1 rs670 against breast tumor clinical parameters, we found the mean age and BMI of different APOA1 rs670 genotype carriers were comparable at baseline." (PMID 23829168, 2013). "In contrast, breast tumors later found responsive to chemotherapy secreted higher amount of apoA1 than tumors non-responsive to chemotherapy during short term ex vivo culture, while non-cancerous tissues secreted highest amount of apoA1." (PMID 23829168, 2013).
chronic hepatitis B (4 papers, 2014 to 2026). "A study showed that hepatitis B virus (HBV) could induce the DNA hypermethylation of CpG island, leading to epigenetic silencing of APOA1 gene expression, and then contribute to the pathogenesis of chronic hepatitis B (CHB)." (PMID 36838613, 2023).
chronic hepatitis C (4 papers, 2010 to 2026). "(2013) for chronic hepatitis C patients included variables such as hyaluronic acid, TGF-β1, α2-macroglobulin, Matrix Metalloproteinase (MMP)-2, apolipoprotein-A1, urea, MMP-1, alpha-fetoprotein, haptoglobin, red blood cell count, hemoglobin, and TIMP-1." (PMID 41551471, 2026). "Blinded serial serum samples (n = 89) from 27 patients with chronic hepatitis C infection undergoing DAA therapy were assayed for viral load, lipids and anti-apoA-1 IgG (AAA1)." (PMID 29423541, 2018).
encephalitis (4 papers, 2010 to 2026). An acute inflammatory process affecting the brain parenchyma. "Compared with the HCs, Hcy (p = 0.002), ApoB (p = 0.004), Lpa (p = 0.045), and ApoB/ApoA-1(p = 0.001) were significantly increased in patients with anti-NMDAR encephalitis." (PMID 37122291, 2023). "At the baseline, there were statistical differences in ApoA-1, ApoB, ApoB/ApoA-1, LPa, and Hcy between the anti-NMDAR encephalitis patients and the HCs." (PMID 37122291, 2023).
gallstones (4 papers, 2019 to 2025). Solid crystalline precipitates in the biliary tract, usually formed in the gallbladder, resulting in the condition of cholelithiasis. "The concentration of apoA-1 did not significantly differ (5.3 vs. 5.9 mg/dL; p = 0.47), while a ninefold lower median concentration of apoB was found in bariatric gallstone patients compared to nonbariatric gallstone patients (1.6 vs. 18.8 mg/dL; p < 0.0001)." (PMID 34677397, 2021). "Interestingly, while apoA1 secreted into bile can assist in solubilizing cholesterol and preventing gallstone formation, the ABCA1/apoA1 system is not directly involved in cholesterol secretion from hepatocytes into bile." (PMID 35300409, 2022).
gestational diabetes (4 papers, 2021 to 2025). Carbohydrate intolerance first diagnosed during pregnancy. "Apolipoprotein A1 (APOA1), the principal apolipoprotein of high-density lipoprotein (HDL), has been predominantly studied in gestational diabetes mellitus due to its canonical role in lipid metabolism." (PMID 40778280, 2025). "In gestational diabetes mellitus (GDM) patients, CEC of maternal GDM-HDL is 25% lower than that of healthy HDL, which is found to be positively correlated with the PON1 activity and contens of APOA1 and APOE." (PMID 37386457, 2023).
Hypocholesterolemia (4 papers, 2019 to 2022). An decreased concentration of cholesterol in the blood. "Red blood cells express a variety of apolipoprotein receptors, in primis the receptor for ApoA1 and B as demonstrated by the hypocholesterolemia and reduced levels of circulating ApoA1 and B expressed by patients with the acquired erythrocytosis Polycythemia Vera." (PMID 31019464, 2019). "Patients had hypocholesterolemia depicted by lower levels of total cholesterol, HDL-C, LDL-C, as well as Apolipoprotein A1 and Apolipoprotein B compared to controls." (PMID 31861992, 2019). "Plasma cholesterol measurements verified the presence of severe hypocholesterolemia in APOA1 KO mice as a result of the genetic lack of APOA1, with plasma total cholesterol levels of 23±1 mg/dl versus 90±2 mg/dl in WT mice (mean±s.e.m., P<0.001)." (PMID 34698355, 2022).
Infertility (4 papers, 2014 to 2023). "The results of proteomic studies on embryos that were successfully implanted in human endometrium showed increased apolipoprotein A1 levels, while immune response-related proteins were once again higher in the infertile groups." (PMID 35719135, 2022).
insomnia (4 papers, 2021 to 2025). A sleep disorder characterized by difficulty in falling asleep and/or remaining asleep. "The results of the two-sample MR analysis demonstrated that the levels of ApoA-1 were causally linked to the risk of insomnia, as determined by IVW." (PMID 38087303, 2023). "The odds ratio (OR) indicated that a one-SD increase in ApoA-1 was causally related to a 24.54% decrease in the risk of insomnia (ApoA-1: N = 10 SNPs, OR: 0.7546, 95% CI: 0.6075–0.9372, P = 0.011)." (PMID 38087303, 2023). "The OR of MVMR suggests that a one-SD increase in ApoA-1 is associated with a 24.00% reduction in the risk of insomnia (ApoA-1, OR: 0.7600, 95% CI: 0.6362–0.9079, P = 0.002)." (PMID 38087303, 2023). "According to the MVMR analysis, there is a causal relationship between an increase in ApoA-1 and a decreased risk of insomnia." (PMID 38087303, 2023). "In this study, a significant causal relationship between serum ApoA-1 levels and insomnia in the European population was found, with each SD increase in ApoA-1 levels reducing the risk of insomnia by 24.54%, suggesting that serum ApoA-1 levels are also a protective factor for insomnia." (PMID 38087303, 2023). "The study utilized scatterplots, forest plots, and funnel plots to analyze the causal relationship between ApoA-1, LPA, and the risk of insomnia." (PMID 38087303, 2023). "The results revealed a causal relationship between ApoA-1 and LPA levels and insomnia in both two-sample MR and MVMR." (PMID 38087303, 2023). "In this study, two-sample MR and MVMR methods were used to investigate the association between serum lipid levels (including TG, ApoA-1, ApoB, LPA) and insomnia in the European population." (PMID 38087303, 2023). "This study suggests that higher levels of ApoA-1 and LPA may contribute to a reduced risk of insomnia." (PMID 38087303, 2023). "Elevated levels of ApoA-1 and LPA were independently and causally associated with the risk of insomnia, suggesting that elevated ApoA-1 and LPA levels may contribute to a reduced risk of insomnia." (PMID 38087303, 2023). "According to relevant reports, apolipoprotein A1 (ApoA-1), apolipoprotein B (ApoB) and lipoprotein A (LPA) are closely related to the occurrence of insomnia events." (PMID 38087303, 2023). "Among them, the expression of F2, HP, FGA, FGB, FGG, and ApoB were upregulated in insomnia patients with wakefulness, and A2M, AHSG, APP, and ApoA1 were downregulated." (PMID 33511209, 2021). "In conclusion, this study proposes that controlling serum ApoA-1 and LPA may help to improve the incidence of insomnia and thus provides a theoretical basis for the clinical treatment of patients with insomnia." (PMID 38087303, 2023). "By MVMR, the results revealed a significant causal relationship between genetic gain in ApoA-1 and LPA and risk of insomnia, but not between TG and ApoB." (PMID 38087303, 2023). "On the other hand, through Western blot experiments, we verified that the expression of FGG, FGB, FGA, APOB, F2, and HP was upregulated in insomnia patients with wakefulness compared with the control, while the expression of A2M, AHSG, and APOA1 was downregulated." (PMID 33511209, 2021). "There was no heterogeneity observed in the Q variable for TG, ApoA-1, ApoB, LPA, and insomnia (MR‒Egger Q, TG: P = 0.996, ApoA-1: P = 0.892, ApoB: P = 0.601, LPA: P = 0.339)." (PMID 38087303, 2023).
ischemia (4 papers, 2016 to 2025). A hypoperfusion of the BLOOD through an organ or tissue caused by a PATHOLOGIC CONSTRICTION or obstruction of its BLOOD VESSELS, or an absence of BLOOD CIRCULATION. "Therefore, as shown in these and previous studies, increased ApoA1 expression after ischemia induces neuroprotective mechanisms." (PMID 41516203, 2025).
non-Hodgkin lymphoma (4 papers, 2020 to 2025). Distinct from Hodgkin lymphoma both morphologically and biologically, non-Hodgkin lymphoma (NHL) is characterized by the absence of Reed-Sternberg cells, can occur at any age, and usually presents as a localized or generalized lymphadenopathy associated with fever and weight loss. "Previous studies have shown that high-density lipoprotein cholesterol (HDL-C) levels are inversely associated with the risk of non-Hodgkin lymphoma, whereas low serum apolipoprotein A1 (APOA1) levels are significantly correlated with poor prognosis in DLBCL patients." (PMID 41041664, 2025).
paroxysmal AF (4 papers, 2020 to 2023). "Subgroup analysis showed lower serum APOA1 in male and female patients who had lower TC, LDL-C, and HDL-C with paroxysmal AF and permanent AF." (PMID 37221493, 2023). "After adjusting for age, TG, TC, LDL-C and HDL-C, Scr, AST, ALT, ALB, APOA1, APOB, and PAB, SUA remained significantly correlated with paroxysmal AF (OR = 1.161, 95% CI 1.039–1.298, P = 0.008)." (PMID 35726017, 2022). "Patients with paroxysmal AF had significantly lower levels of TG, TC, LDL-C, HDL-C, APOA1, and APOB (P < 0.05), and significantly higher levels of AST, Scr, and SUA (P < 0.05)." (PMID 36031606, 2022). "Furthermore, subgroup analysis showed lower serum APOA1 in male and female patients who had lower TC, LDL-C, and HDL-C with paroxysmal AF and permanent AF." (PMID 37221493, 2023).
periodontitis (4 papers, 2015 to 2023). An acute or chronic inflammatory process that affects the tissues that surround and support the teeth. "The IVW estimates showed that genetically predicted Apolipoprotein A1 (apo A1) [odds ratio (OR)=1.158, 95% confidence interval (CI)=1.007–1.331, P-value=0.040] was potentially associated with the risk of periodontitis, but the statistical power of the results was low." (PMID 37583432, 2023).
rheumatic disease (4 papers, 2012 to 2024). "There is increasing evidence to show that the atherogenic ApoB/ApoA1 ratio is an independent prospective predictor of cardiovascular events both in the general population and in patients with rheumatic diseases." (PMID 32298352, 2020). "In addition, an elevated ApoB/ApoA1 ratio also increased the incidence of aortic aneurysm (especially AAA), non-rheumatic valve diseases, and atrial flutter and fibrillation." (PMID 38310324, 2024).
abdominal aortic aneurysm (3 papers, 2017 to 2023). Enlargement and ballooning of the vessel that supplies arterial blood to the abdomen, pelvis and legs. "A recently published study showed that the APOA1 oxidation is linked with the dysfunction in high-density lipoproteins in human abdominal aortic aneurysm." (PMID 36922793, 2023).
African trypanosomiasis (3 papers, 2021 to 2024). "Of the 38 African trypanosomiasis ID5143 pathway genes nine could not be detected including Kng1 and 2 encoding the kallikrein-kinin hormonal cascade in addition to Il12b and the E-selectin gene Sele while the levels Il12a, Apoa1, Fasl and Plcb2 message were subthreshold." (PMID 34762691, 2021).
aortic valve stenosis (3 papers, 2019 to 2025). Aortic valve stenosis (AVS) is a condition characterized by narrowing of the heart's aortic valve opening. "Moreover, the results of a study encompassing 17,745 participants, with a follow-up period of 19.8 years, indicated that an increase of 30% in the APOB/APOA1 ratio was associated with a 30% rise in the risk of aortic valve stenosis." (PMID 40787622, 2025).
cardiomyopathy (3 papers, 2018 to 2024). A disease of the heart muscle or myocardium proper. "Our GO and KEGG analyses revealed that HECTD4 and MYL2 are associated with cardiomyopathy, suggesting that the connection between AKT1 and the ApoA1 level has a direct connection to CVDs." (PMID 36140721, 2022). "The functional analysis of our data for two new loci (HECTD4 and MYL2) shows that they are associated with cardiomyopathy, suggesting that the association between AKT1 and the ApoA1 level has a direct connection to CVDs." (PMID 36140721, 2022). "Furthermore, GO and KEGG analyses revealed that HECTD4 and MYL2 are associated with cardiomyopathy, suggesting that the association between AKT1 and the ApoA1 level has a direct connection with CVDs." (PMID 36140721, 2022).
cataract (3 papers, 2021 to 2024). Partial or complete opacity of the crystalline lens of one or both eyes that decreases visual acuity and eventually results in blindness. "APOA1, APOC3, and APOE have been shown to be elevated in the AH of POAG patients as compared to patients with cataracts." (PMID 34602085, 2021). "Conversely, female POAG patients had significantly greater levels of APOA1 (FC = 1.36; p < 0.01), APOA2 (FC = 1.21; p = 0.03), APOA4 (FC = 1.30; p = 0.04), APOC3 (FC = 1.38; p = 0.01), and APOD (FC = 1.20; p = 0.04) compared to cataract patients." (PMID 34602085, 2021).
celiac disease (3 papers, 2019 to 2025). An autoimmune genetic disorder with an unknown pattern of inheritance that primarily affects the digestive tract. "Using quantitative PCR (qPCR) confirmed the reduction in sucrase-isomaltase (SI) and APOA1 genes expression levels in celiac disease." (PMID 31700112, 2019).
cholestasis (3 papers, 2010 to 2024). Impairment of the bile flow caused by obstruction within the liver, or outside the liver in the bile duct system. "It has been well-established both in mice and humans that cholestasis leads to a decrease in HDL and its main apolipoprotein apoA1." (PMID 20126555, 2010). "Additionally, HDL-C exhibited a strong correlation with ApoA1 in both jaundice and non-jaundice cholestasis cases." (PMID 39376224, 2024).
colorectal adenoma (3 papers, 2019 to 2022). An adenoma that arises from the colon or rectum. "It is reported that high serum APOA1 level has been associated with a decreased risk of several cancers including colorectal adenomas and CRC." (PMID 35945555, 2022).
coronary artery calcification (3 papers, 2012 to 2022). Calcification of the coronary artery, used as a measure of coronary atherosclerosis, a risk factor for myocardial infarction. "Moreover, in otherwise healthy obese persons, anti-apoA-1 antibodies were predictive of coronary artery calcification." (PMID 34888742, 2022).
esophageal cancer (3 papers, 2021 to 2024). A primary or metastatic malignant neoplasm involving the esophagus. "Similarly, reduced plasma levels of APOA1 are associated with metastasis and poor prognosis across several cancers, such as ovarian, colorectal, and esophageal cancers." (PMID 39399493, 2024).
Gilbert syndrome (3 papers, 2008 to 2011). An autosomal recessive inherited disorder characterized by unconjugated hyperbilirubinemia, resulting in harmless intermittent jaundice. "Among the 38 (0.51%) tests with RFPN, 31 (0.41%) were related to low haptoglobin, five to high ApoA1, two to high GGT, one to low ApoA1 and one to high bilirubin with proven Gilbert's syndrome." (PMID 21492460, 2011). "Majority of high-risk profiles (24/33) were abnormally low haptoglobin (hemolysis or anhaptoglobinemia), 4 subjects had abnormally high apoA1 value, 1 abnormally low ApoA1, 2 abnormally high GGT, one Gilbert syndrome with 72 micromol of unconjugated bilirubin, and one abnormally high A2 M." (PMID 20412588, 2010).
hepatitis C (3 papers, 2021 to 2025). "Another recent study in patients with hepatitis C showed that patients who displayed anti-apoA-1 positivity also had significantly lower apoA-1 levels." (PMID 34888742, 2022).
kidney transplant (3 papers, 2013 to 2025). A surgical procedure in which one or both kidneys from a donor are implanted into a recipient. "Apolipoprotein A1 (APOA1): APOA1 in plasma was identified as a potential biomarker for acute cellular rejection in kidney transplant recipients utilizing surface-enhanced laser desorption/ionization time-of-flight mass spectrometry (SELDI-TOF MS)." (PMID 40005378, 2025). "Moreover, the prognostic value of APOA1 rs670 A/A carriage in the worse post-surgery outcomes was most evident in lymph node-negative patients." (PMID 23829168, 2013).
leukocytosis (3 papers, 2020 to 2025).